SF3B1 (splicing factor 3b subunit 1)
Description:
Component of the 17S U2 SnRNP complex of the spliceosome, a large ribonucleoprotein complex that removes introns from transcribed pre-mRNAs. The 17S U2 SnRNP complex (1) directly participates in early spliceosome assembly and (2) mediates recognition of the intron branch site during pre-mRNA splicing by promoting the selection of the pre-mRNA branch-site adenosine, the nucleophile for the first step of splicing. Within the 17S U2 SnRNP complex, SF3B1 is part of the SF3B subcomplex, which is required for 'A' complex assembly formed by the stable binding of U2 snRNP to the branchpoint sequence in pre-mRNA. Sequence independent binding of SF3A and SF3B subcomplexes upstream of the branch site is essential, it may anchor U2 snRNP to the pre-mRNA. May also be involved in the assembly of the 'E' complex. Also acts as a component of the minor spliceosome, which is involved in the splicing of U12-type introns in pre-mRNAs. Together with other U2 snRNP complex components may also play a role in the selective processing of microRNAs (miRNAs) from the long primary miRNA transcript, pri-miR-17-92 (By similarity).
Synonyms: SF3b155; SAP155; PRPF10; Prp10; Hsh155; MDS
Tractability: Small molecule: a structure with a bound ligand is known. PROTAC: UniProt records ubiquitination sites on it; ubiquitination databases record sites on it; its protein half-life has been measured.
Target class: Other nuclear protein
Gene: Protein-coding gene on chromosome 2 (197,388,515 to 197,435,079, reverse strand). Ensembl gene ENSG00000115524.
Subcellular location: Nucleus; Nucleus speckle
Subcellular location (Human Protein Atlas): Nuclear speckles
Pathways (Reactome):
Metabolism of RNA: mRNA Polyadenylation; mRNA Splicing - Major Pathway; mRNA Splicing - Minor Pathway
Chromatin organization: CHD1 and CHD2 subfamily
Disease: Dengue Virus-Host Interactions
Gene expression (Transcription): B-WICH complex positively regulates rRNA expression
Gene Ontology:
Molecular function: pre-mRNA binding; protein binding; RNA binding; splicing factor binding; mRNA binding
Biological process: mRNA splicing, via spliceosome; positive regulation of transcription by RNA polymerase III; spliceosomal complex assembly; chromatin remodeling; mRNA cis splicing, via spliceosome; positive regulation of transcription by RNA polymerase I; positive regulation of transcription by RNA polymerase II; RNA splicing; RNA splicing, via transesterification reactions; spliceosomal snRNP assembly; spliceosome conformational change to release U4 (or U4atac) and U1 (or U11); U2-type prespliceosome assembly
Cellular component: B-WICH complex; catalytic step 2 spliceosome; nuclear speck; nucleus; precatalytic spliceosome; spliceosomal complex; U11/U12 snRNP; U12-type catalytic step 2 spliceosome; U12-type precatalytic spliceosome; U12-type spliceosomal complex; U2 snRNP; U2-type catalytic step 1 spliceosome; U2-type precatalytic spliceosome; U2-type spliceosomal complex; nucleolus; nucleoplasm; U2-type prespliceosome; nuclear lumen
Genetic constraint (gnomAD): Loss-of-function variants: 6 observed, 118.48 expected, observed/expected ratio (o/e) 0.0506, 90% interval 0.027 to 0.1. The upper end of that interval is the gene's LOEUF score, 0.1, which puts it in group 1 of 6, group 1 being the genes least tolerant of losing a copy. Missense variants: 396 observed, 1,406.6 expected, observed/expected ratio (o/e) 0.28, 90% interval 0.26 to 0.31. Synonymous variants: 409 observed, 466.6 expected, observed/expected ratio (o/e) 0.88, 90% interval 0.81 to 0.95.
Cancer hallmarks: escaping programmed cell death (promotes)
Homologues: Orthologues: dog SF3B1 (100% identical), mouse Sf3b1 (100% identical), rat Sf3b1 (100% identical), guinea pig SF3B1 (99% identical), macaque SF3B1 (99% identical), tropical clawed frog sf3b1 (97% identical), zebrafish sf3b1 (94% identical), chimpanzee SF3B1 (91% identical), Drosophila melanogaster Sf3b1 (79% identical), Caenorhabditis elegans sftb-1 (68% identical).
Diseases named in the same sentence as SF3B1 in open-access papers:
SF3B1 is named in the same sentence as 176 diseases in open-access papers, as found by Europe PMC text mining. Sharing a sentence is not in itself a finding about the gene and the disease. The quoted sentences say what the papers report.
myelodysplastic syndrome (174 papers, 2012 to 2026). A clonal hematopoietic disorder characterized by dysplasia and ineffective hematopoiesis in one or more of the hematopoietic cell lines. "SF3B1-mutated myelodysplastic syndrome (MDS) is a distinct entity associated with a favorable prognosis." (PMID 41683845, 2026). "Although its application in FGFR field remains nascent, GoT-Splice has successfully mapped SF3B1 mutation-associated splicing disruptions in myelodysplastic syndromes." (PMID 41584352, 2026). "Among them, the Phase I clinical trial of H3B-8800 observed alleviation of red blood cell transfusion dependence in a subset of myelodysplastic syndrome (MDS) patients harboring SF3B1 missense mutations." (PMID 41268214, 2025). "According to the 2022 International Consensus Classification of myeloid neoplasms and acute leukemia, a diagnosis of SF3B1-mutant myelodysplastic syndrome can be made when an SF3B1 mutation is present and RSs comprise ≥5% of erythroid precursors." (PMID 40980042, 2025). "Recent studies have demonstrated both the significant correlation between SF3B1 mutations and myelodysplastic neoplasms and a relative prognostic homogeneity among mutation-positive cases." (PMID 41283234, 2025). "Myelodysplastic syndromes with somatic mutations in the splicing factor SF3B1 gene (MDS-SF3B1) result in RNA mis-splicing, erythroid dysplasia and ultimately refractory anemia." (PMID 40858805, 2025). "The SF3B1 K700E mutation (lysine to glutamic acid) is common in myelodysplastic syndrome and other blood disorders." (PMID 41058062, 2025). "Here the authors find that erythroblasts of myelodysplastic syndromes with SF3B1 mutation leading to inefficient erythropoiesis show DNA replication stress with accelerated forks and reduced R-loops." (PMID 38589367, 2024). "Chronic myelomonocytic leukemia (CMML) and myelodysplastic syndromes (MDS) with ring sideroblasts (RS) or SF3B1 mutation (MDS-RS/SF3B1) differ in many clinical features, but share others, such as anemia." (PMID 39011475, 2024). "It has been shown that mutations in the splicing factor 3b subunit 1 encoded by the SF3B1 gene are frequent in myelodysplastic neoplasms (MDS)." (PMID 39200378, 2024). "The role of SUGP1 is only beginning to be understood, but it was recently identified as a binding partner of SF3B1, a spliceosome component that is commonly mutated in cancers and myelodysplastic syndrome." (PMID 38880245, 2024). "Studies in patients with myelodysplastic neoplasms (MDS) demonstrated that patients carrying an SF3B1 mutation have a significantly better prognosis compared with patients without SF3B1 mutations." (PMID 38736877, 2024). "WHO2022 recognizes myelodysplastic syndrome (MDS) with SF3B1 mutation as one of the MDS with defining genetic abnormalities." (PMID 38485897, 2024). "Mutations in the SF3B1 subunit of the U2 snRNP cause selection of alternative splice sites and are implicated in diseases such as myelodysplastic syndrome (MDS)." (PMID 39187383, 2024). "Mutations in SF3B1 have been seen in advanced chronic lymphocytic leukemia, myelodysplastic syndromes and breast cancer." (PMID 38175637, 2024). "SF3B1 mutations have been identified in several myeloid malignancies, particularly myelodysplastic syndromes (MDS), as well as other blood cancers, breast cancer, and uveal melanoma." (PMID 37623489, 2023). "For example, a common mutation in SF3B1 (K700E) contributes to the expansion of long-term HSCs (LT-HSCs) and the phenotype acquisition of myelodysplastic syndrome (MDS)." (PMID 37299568, 2023). "Mutations in SF3B1 are the most frequent and relevant spliceosome mutations in hematological diseases, including myelodysplastic syndromes." (PMID 38012150, 2023). "SF3B1 mutations cause aberrant splicing and activation of inflammatory immune signaling in myelodysplastic syndromes." (PMID 38012150, 2023).
myelodysplastic syndrome (continued). "Successively, PNA-PCR clamping and Sanger sequencing were used to blind test 90 DNA from patients affected by myelodysplastic syndromes and myeloproliferative neoplasms for the SF3B1 p.Lys700Glu mutation." (PMID 35268357, 2022). "The outcomes of myelodysplastic syndrome (MDS) patients with SF3B1 mutation, despite identified as a favorable prognostic biomarker, are variable." (PMID 35832562, 2022). "Mutations in SF3B1 are found in 20% of myelodysplastic syndromes and 5–10% of myeloproliferative neoplasms, where they are considered important for diagnosis and therapy decisions." (PMID 35268357, 2022). "For example, the myelodysplastic syndromes are a group of blood cancers often caused by mutations in splicing proteins, such as SF3B1." (PMID 36040792, 2022). "The detection of SF3B1 mutation assigns, depending on clinical and biological features, to a myelodysplastic neoplasm or a myelodysplastic/myeloproliferative neoplasm." (PMID 35885655, 2022). "Among these, SF3B1 mutations have acquired great interest, especially in myelodysplastic syndromes, as they identify a subgroup of patients who can benefit from personalized therapy." (PMID 36230848, 2022). "In particular, the mis-splicing of ABCB7 has been proposed to drive ring sideroblasts formation in patients affected by myelodysplastic syndromes with SF3B1 mutation." (PMID 36230848, 2022). "We analyzed a set of CD34+ hematopoietic stem cells and myelodysplastic syndrome samples and found a set of genes whose isoform diversity change is associated with SF3B1 mutations." (PMID 34499147, 2021). "SF3B1 mutations have been identified in subsets of solid tumors, as well as in myelodysplastic syndrome and chronic lymphocytic leukemia." (PMID 34102999, 2021). "Most recently, the International Working Group for the Prognosis of Myelodysplastic Syndromes (IWG-PM) provided supporting evidence that shows the recognition of SF3B1-mutant MDS as a distinct diagnostic entity." (PMID 34360561, 2021). "Even though the SF3B1 gene is one of many cellular genes involved in RNA splicing, it has been specifically identified as a commonly mutated gene in myelodysplastic syndrome (MDS), at frequencies of 25 to 30% (47, –, 49)." (PMID 33597212, 2021). "It was early observed in patients with myelodysplastic syndrome that SF3B1 and SRFS2 mutations are associated with a downregulated mirtronic miR-3605-5p and miR-4728-5p." (PMID 33875796, 2021). "Genes encoding splicing factors are frequently mutated in myelodysplastic syndromes, in which SF3B1 mutations are the most frequent." (PMID 32168916, 2020). "The International Working Group for the Prognosis of Myelodysplastic Syndromes (IWG-PM) has recently recognized SF3B1-mutated MDS as a distinct nosologic entity, characterized by ring sideroblasts, ineffective erythropoiesis, and indolent clinical course." (PMID 32414002, 2020). "For example, mutations in U2AF1, SRSF2, ZRSR2, and SF3B1 have been identified in myelodysplastic syndromes, chronic lymphocytic leukemia, uveal melanoma, and breast cancer." (PMID 33040078, 2020). "In this study, we identified and characterized a novel SF3B1 transcript that is specifically produced in neoplasms carrying an SF3B1 mutation, including in myelodysplastic syndromes." (PMID 32168916, 2020). "Several studies have identified mutations in SF3B1 in subsets of solid tumors, as well as in myelodysplastic syndrome and chronic lymphocytic leukemia (CLL), in which they occurred in almost 15% of the reported cases." (PMID 30847022, 2019). "SF3A2 is part of the U2 snRNP, and another member of this complex (SF3B1) is recurrently mutated in myelodysplastic syndrome, acute myeloid leukemia, and chronic lymphocytic leukemia." (PMID 30867899, 2019). "In uveal melanoma and myelodysplastic syndrome, SF3B1 mutations are associated with a better prognosis, whereas in CLL, SF3B1 mutations are correlated with a worse prognosis." (PMID 30847022, 2019).
myelodysplastic syndrome (continued). "Somatic heterozygous mutations in SF3B1 are particularly prevalent in myelodysplastic syndromes (MDS)—up to 80% in refractory anemia with ring sideroblasts; and in 15% of chronic lymphocytic leukemia (CLL)." (PMID 31634348, 2019). "The frequency of SF3B1 mutations is particularly high among the unique subtypes of myelodysplastic syndrome that are characterized by increased ring sideroblasts, in which mutation frequencies of 66.7–79% have been reported." (PMID 29383138, 2017). "There was also a correlation between alterations in SF3B1, which is frequently mutated in myelodysplastic syndromes, and the CD-2 subgroup." (PMID 28234347, 2017). "For example, the SF3B1 protein is mutated both in chronic lymphocytic leukemia and myelodysplastic syndrome, and it is presently unclear how loss of this function promotes tumor initiation/progression." (PMID 27315300, 2016). "One of the most studied cases is SF3B1, which is mutated in ~20 % of patients with myelodysplastic syndromes (MDS)." (PMID 27287018, 2016). "It has been only observed in patients with myelodysplastic syndrome that SF3B1 and SRFS2 mutations are associated with a downregulated expression of miRNAs derived from the putative 5′-tailed mirtrons hsa-miR-3605-5p and hsa-miR-4728-5p, respectively." (PMID 27019673, 2016). "Given that SF3B1 knockout mouse cannot mimic defects seen in myelodysplastic syndromes, mutations in SF3B1 are likely gain-of-function mutations." (PMID 26575292, 2015). "For example, SF3B1 (Splicing factor 3B subunit 1) is highly mutated in various hematological malignancies such as chronic lymphocytic leukemia and myelodysplastic syndromes." (PMID 26303214, 2015). "Lastly, recurrent somatically acquired mutations of the SF3B1 gene can be demonstrated in subtypes of myelodysplastic syndromes in which ring sideroblasts are a prominent feature." (PMID 23209713, 2012). "SF3B1 is frequently mutated in myelodysplastic syndrome and various solid tumors." (PMID 41427026, 2025). "For example, SF3B1 mutations in myelodysplastic syndromes specifically impair the erythroid lineage by inducing mis-splicing of MAP3K7, which leads to p38 MAPK inactivation and premature downregulation of GATA1, thereby blocking terminal erythroid differentiation." (PMID 41360772, 2025). "SF3B1 mutation is common in myelodysplastic syndrome and other blood disorders." (PMID 40027643, 2025). "In myeloid malignancies, mutations in SF3B1 are most prevalent in myelodysplastic syndromes (MDS)." (PMID 39584923, 2024). "Further studies are also required to assess the impact of this drug on other myeloid neoplasms associated with anemia such as myelodysplastic syndromes with ring sideroblasts or SF3B1 mutation, especially those with co-expression of a JAK2 mutation and thrombocytosis." (PMID 38983933, 2024). "Mutations in SF3B1 are the most common across multiple tumor types, mainly found in myelodysplastic syndrome and other hematologic malignancies, uveal melanoma and breast cancer, where its high mutational frequency altered the capacity of the spliceosome to recognize the pre-RNA pattern." (PMID 37880792, 2023). "As we also demonstrated increased cen-R-loop formation in K562 SF3B1-MT cells, we speculate that SF3B1 mutation may also induce CIN via cen-R-loop accumulation that contributes to the pathogenesis of myelodysplastic syndrome (MDS)." (PMID 37463047, 2023). "Genetic alterations in RNA-binding proteins can lead to genetic diseases, including amyotrophic lateral sclerosis caused by fused-in-sarcoma (FUS)/TAR DNA binding protein-43 (TDP-43) mutations, and myelodysplastic syndromes caused by U2AF35/ splicing factor 3b subunit 1 (SF3B1) mutations." (PMID 37480049, 2023). "Notably, SF3B1 mutation was mostly found in myelodysplastic syndromes (MDS), chronic lymphocytic leukemia, or MM with potential myeloid neoplasm." (PMID 36230837, 2022).
myelodysplastic syndrome (continued). "SF3B1 (Splicing Factor 3b, Subunit 1) is the most frequently mutated splicing gene in cancer, recurrently found in hematological malignancies (28% in myelodysplastic syndromes, 15% in chronic lymphocytic leukemia) and 23% of uveal melanoma (UM), the most common primary intraocular tumor in adults." (PMID 35565242, 2022). "Of these non-JAK2 mutation cases, the NRAS, CSF3R and TET2 c.4319_4329del; p.Arg1440Hisfs*34 were in the context of therapy-related disease; the remaining 4 other mutations (TET2, TET2, DNMT3A, and SF3B1) were in the context of disease progression from myelodysplastic syndrome." (PMID 36323674, 2022). "Mutations in SF3B1 are found in most patients with myelodysplastic syndrome (MDS)." (PMID 34439339, 2021). "SF3B1 encodes a subunit of the spliceosome and mutations in this gene have been identified as potentially interesting treatment targets after having been observed in myelodysplastic syndromes and chronic lymphocytic leukemia." (PMID 32926574, 2020). "Based on its ability to target both tRNA metabolism and splicing, we propose a new therapeutic application for the riboside analogue 8-azaguanine in treating patients harbouring SF3B1 mutations, such as breast cancer, uveal melanoma, myelodysplastic syndromes, acute myeloid leukaemia and beyond." (PMID 30804405, 2019). "SF3B1 mutations have been described as driver mutation in several myeloid malignancies including chronic lymphocytic leukemia, chronic myelomonocytic leukemia and myelodysplastic syndrome 23,24." (PMID 31632503, 2019). "Mutations in the splicing factor SF3B1 are the most common across multiple tumour types, and are found at particularly high frequencies in myelodysplastic syndrome (MDS), chronic myeloid leukaemia (CLL), uveal melanoma (UV), pancreatic cancer and breast cancer." (PMID 29848666, 2018). "The SF3B1 gene encodes subunit 1 of the splicing factor 3b, which is important for anchoring the spliceosome to the precursor mRNA, and is the most commonly mutated gene found in myelodysplastic syndrome." (PMID 29383138, 2017). "SF3B1 has been found to have mutations in myelodysplastic syndrome and in leukemia." (PMID 26575292, 2015). "SF3B1 gene mutations are prevalent in myelodysplastic syndrome (MDS) and define a distinct disease subtype." (PMID 40158006, 2025). "Additionally, in 2022, the International Consensus Classification (ICC) for Myeloid Neoplasms and Acute Leukemias introduced an updated framework for myelodysplastic neoplasms that further foregrounds molecular and cytogenetic features (e.g., SF3B1 mutation, isolated del(5q))." (PMID 41283234, 2025). "SF3B1 is the most frequently mutated splicing factor in myelodysplastic syndrome (MDS)—a clonal hematopoietic disorder with a variable risk of leukemic transformation." (PMID 40001461, 2025). "Pathogenic SF3B1 mutations are most frequent in myelodysplastic syndromes (MDS) and are also found in acute myeloid leukemia (AML), chronic lymphocytic leukemia (CLL) and several solid tumors, such as breast cancer (BRCA) and uveal melanoma (UVM)." (PMID 41406100, 2025). "SF3B1 mutations, which are prevalent in myelodysplastic syndrome (MDS) and leukemia, result in missplicing of Brd9 and a subsequent loss of ncBAF at CTCF-associated loci." (PMID 40523422, 2025). "SF3B1 mutation was observed in 90% of patients with myelodysplastic syndrome (MDS) with ring sideroblasts, which is characterized by anemia, iron-rich mitochondria surrounding the nuclei of erythroid precursors, and a favorable prognosis." (PMID 37342192, 2023). "Among the most common genetic alterations in the myelodysplastic syndromes (MDS) are mutations in the spliceosome gene SF3B1." (PMID 37090662, 2023). "SF3B1 mutation has been detected in 30% of patients with myelodysplastic syndrome (MDS) and in 80% of patients presenting MDS subtype with ringed sideroblasts (RARS)." (PMID 37875914, 2023).